CD38 (CD38 molecule)
Diseases named in the same sentence as CD38 in open-access papers (continued):
Sharing a sentence is not in itself a finding about the gene and the disease.
COVID-19 (continued). "While increased CD38 expression across monocyte subsets was a general feature unrelated to disease severity, higher levels of CCR2 on iMonos, as well as lower levels of HLA-DR and CD86 with increased expression of CD163 in all monocyte subsets, were found in severe COVID-19." (PMID 33479167, 2021). "In addition to showing that COVID-19 has decreased levels of CD4+ and CD8+ T cells, it has also been shown that the levels of CD4 + T cells expressing CD38− and HLA-DR−, and CD8+ T cells and CD4+PD-1+ T cells, were higher in the proportion of patients with severe COVID-19 compared to healthy people." (PMID 34359987, 2021). "Furthermore, we found that elevated fraction of HLA-DR+CD38hi rather than HLA-DR+CD38+ CD8+ T cells were persistently accumulated in COVID-19 patients, especially in severe and critical cases." (PMID 34567001, 2021). "Looking at the activation as measured by HLA-DR and CD38 expression, we observed an increase of HLA-DR+CD38+ cells in the TM and EM subset of CD8+ T cells and in the CM and TM subset of CD4+ T cells in both COVID-19 and malaria patients compared to healthy controls." (PMID 32983106, 2020). "Phenotyping A2/S269+CD8+ T cells from COVID-19 convalescents ex vivo showed that A2/S269+CD8+ T cells were predominantly negative for CD38, HLA-DR, PD-1, and CD71 activation markers, although the majority of total CD8+ T cells expressed granzymes and/or perforin." (PMID 32913053, 2020). "However, we did not observe higher rates of COVID-19 among recipients of anti-CD38 treatment." (PMID 38092996, 2024). "Furthermore, CD38 was strongly upregulated on CD8+ T cells in influenza but not COVID-19 patients." (PMID 35371005, 2022). "Regarding the distinct expression patterns of CD38 and HLA-DR between natural infection and vaccination and since impairment of dendritic functions in patients with COVID-19 has been reported, the lack of impairment of dendritic cells might lead to strong stimulation of CD8+ T cells by vaccination." (PMID 35572546, 2022). "In addition, effector (PD-1+, CD38+) CD4+ (which are playing a key role for mucosal immunity) and CD8+ T cells and CD8+CD103+ T cells (tissue resident memory) were increased in gastrointestinal biopsies of COVID-19 recovered individuals as compared to controls." (PMID 35630492, 2022). "Using the calculation of relative frequencies of COVID-19 throughout the 6-month follow-up, the results were positive for the anti-CD20 group of patients (p = 0.031), but negative for the anti-CD38 (p = > 0.9) and HSCT/CAR-T group (p = 0.2), respectively." (PMID 38092996, 2024). "Hence, the expression of CD38+ on CD3+CD8+ cells with or without simultaneous expression of PD1 on CD3+CD4+ cells may be utilized as a biomarker of a fatal outcome in hospitalized patients with COVID-19." (PMID 36992243, 2023). "Frequencies of CD38+ cells in CD8+ naïve and central memory CD8+ T cells decreased significantly in moderate and severe COVID-19 non-HD patients, but not in moderate/severe COVID-19 HD patients." (PMID 35265078, 2022). "While in controls double positive cells were absent or present in very low percent, in COVID-19 patients a large number of monocytes co-expressing CD23 and CD38 were found in intermediate and nonclassical subsets." (PMID 33382687, 2020). "However, both pregnant and nonpregnant women had an increase in HLA-DR+CD38+ CD8+ T cells and CD14+ classical monocytes during acute COVID-19, as compared with their respective healthy group." (PMID 37036008, 2023). "Interestingly, we detected a significant increase in the CD38+CD8+ effector memory and TEMRA T cell population in the moderate/severe COVID-19 HD cohort, which was not the case in the COVID-19 non-HD patients." (PMID 35265078, 2022). "Interestingly in the COVID-19(+) group there were positive correlations RE-LYMP with CD25 and CD45RO markers in both CD4 and CD8+ cells without correlations with markers CD38 and HLA-DR." (PMID 33419040, 2021).
COVID-19 (continued). "A major region of this tSNE map present in COVID-19 patients, but not HDs or RDs, encompasses CD8 T cells enriched for expression of CD38, HLA-DR, KI67, CD39, and PD-1, highlighting the coexpression of these activation markers with other features, including CD95 (i.e., FAS)." (PMID 32669297, 2020). "Because treatments received by MM group could cause specific immune dysfunction impairing immune response to COVID-19 vaccines, we first compared the levels of specific SARS-CoV-2 IgG antibodies and neutralization capacity in MM patients receiving or not daratumumab (anti-CD38 therapy)." (PMID 35961779, 2022).
acute myeloid leukemia (154 papers, 2010 to 2026). Acute myeloid leukemia (AML) is a group of neoplasms arising from precursor cells committed to the myeloid cell-line differentiation. "Here we present the integrated metabolome, lipidome and transcriptome of human adult HSPCs (lineage−, CD34+, CD38−) upon differentiation, ageing and acute myeloid leukaemia." (PMID 40664811, 2025). "The augmented internalization of the targeted nanoconstruct in Burkitt’s lymphoma cells in comparison to the one in healthy B-Lymphocytes and in a CD38− acute myeloid leukemia (HL60) demonstrates the targeting efficiency of anti-CD38 lipid-coated ZnO NCs." (PMID 38353903, 2024). "CD38 expression has been observed in acute myeloid leukemia (AML) and acute lymphoblastic leukemia (ALL)." (PMID 39046511, 2024). "Propofol inhibited the differentiation capacity of acute myeloid leukaemia stem cells (CD34+/CD38− subsets)In presence of Propofol, the activity of Akt/mTOR, and the Wnt/β‐catenin pathways were diminished." (PMID 37156724, 2023). "In 1994 Lapidot and coworkers first identified a subpopulation of CD34+CD38−- CSCs in acute myeloid leukemia (AML)." (PMID 36230480, 2022). "CD38 is also often highly expressed in other hematological malignancies, e.g. acute myeloid leukemia (AML), and chronic lymphocytic leukemia (CLL)." (PMID 36405759, 2022). "The cancer stem cell (CSC) paradigm emerged from investigating a subpopulation of less-differentiated CD34+/CD38- cells possessing stem cell-like renewal ability and robust malignant-initiating capacity in acute myeloid leukemia (AML)." (PMID 36627897, 2022). "(E) IRAK4 expression in sorted HSCs (Lineage –ve, CD34+, CD38−) cells from MDS/acute myeloid leukemia (AML) cases (N=9) and controls (N=5)." (PMID 36040792, 2022). "As previously reported, the immature KG1 acute myeloid leukemia cell line overexpressed LSC-associated and ABCB1 genes and made up an important CD34 + CD38− LSC subpopulation (10.4%)." (PMID 35628366, 2022). "The presence of CSCs has been demonstrated for the first time in human acute myeloid leukaemia as a CD34+CD38− population." (PMID 34075691, 2021). "The continued relevance of the CD34/CD38 marker combination is exemplified in two recently published studies regarding the prognostic significance of a high CD34+/CD38- stem cell burden in patients with myelodysplastic syndromes and acute myeloid leukemia." (PMID 33878141, 2021). "The first isolation of CSCs by fluorescence-activated cell sorting using CD34 and CD38 (CD34+CD38−) surface marker expression was in acute myeloid leukemia and dates back to 1994." (PMID 33477367, 2021). "For example, targeting the overexpressed CD123 marker on CD34+ CD38– leukemic stem cells in acute myelogenous leukemia impairs leukemic stem cells homing to the bone marrow and induces a decrease in the overall AML cell repopulation." (PMID 33362856, 2020). "CSCs were first isolated (CD34+CD38−) from Acute Myeloid Leukemia (AML) patient samples in late 90s." (PMID 32296643, 2020). "CSCs were initially identified in acute myeloid leukemia (AML) as a CD34+ CD38- subpopulation capable of initiating leukemia after engraftment in immunodeficient mice." (PMID 29491834, 2018). "In contrast, one patient suffering underlying acute myeloid leukemia who died during H3N2 infection displayed prolonged and increasing frequency of CD38+PD-1+ expression on CD8+ T cells, comparable to that characteristic of the fatal H7N9 cases." (PMID 29483513, 2018). "About 20% of SCID-Rasa3−/− mice develop a preleukemia characterized by a massive infiltration of bone marrow and spleen with CD117+ Sca-1+ CD38+ cells, a phenotype very similar to acute myeloid leukemia in man." (PMID 24967784, 2014). "Almost two decades later, a CD34+CD38− subpopulation of cells were isolated in acute myeloid leukaemia which, when transplanted into NOD/SCID mice, were capable of initiating acute myeloid leukaemia." (PMID 23533441, 2013).
acute myeloid leukemia (continued). "CSCs were first demonstrated in human acute myeloid leukemia (AML) when investigators found that the ability to initiate tumors by transplantation of AML cells into NOD/SCID mice was limited to a CD34+/CD38− subpopulation of leukemic cells." (PMID 24179490, 2013). "This technique was first used by Bonnet and Dick in 1997 when they demonstrated that only the CD34+CD38− subset of cells were capable of initiating human acute myeloid leukemia (AML) in immune-compromised mouse models." (PMID 20936110, 2011). "Resistance of CSC populations to therapy was first reported in human acute myeloid leukaemia CD34+/CD38− stem cells." (PMID 20332776, 2010). "This interaction is particularly significant as TFEB acts as a tumor suppressor in acute myeloid leukaemia by promoting myeloid differentiation and cell death, thereby emphasising the critical nature of the CD38–MYC relationship and introducing additional complexity." (PMID 39364393, 2024). "CD34+CD38- CSCs were first recognized in acute myeloid leukemia." (PMID 37509281, 2023). "CD34 + CD38− acute myeloid leukemia (AML) cells were used to identify CSCs." (PMID 36675306, 2023). "Acute myeloid leukemia (AML) is an aggressive heterogenous disease arising from the accumulation and clonal expansion of somatic-driven mutations in CD34+/CD38- hematopoietic progenitors, which demonstrate increased proliferation, survival, and impaired maturation capacity." (PMID 37108308, 2023). "CD38 expression is very variable in acute myeloid leukaemia (AML)." (PMID 36077708, 2022). "Acute myeloid leukemia (AML) LSCs predominantly reside in the CD34+CD38− fraction." (PMID 32872365, 2020). "The first evidence for CSCs came in a 1994 study, which proved that one CD34+/CD38-cell from human acute myeloid leukemia (AML) could reinitiate leukemia in mice." (PMID 31277278, 2019). "Studies have reported that N-cadherin is expressed on primitive sub-populations of leukaemic cells including patient-derived CD34+ CD38− chronic myeloid leukaemia (CML) cells and CD34+ CD38− CD123+ acute myeloid leukaemia (AML) cells, suggesting that N-cadherin is a marker of LSCs." (PMID 30285678, 2018). "CD38 is not only expressed on MM cells but also in other hematologic malignancies derived from both lymphoid and myeloid lineages including non‐Hodgkin's lymphoma 129, acute myeloid leukemia 55, acute lymphoblastic leukemia 55, as well as in CLL." (PMID 26864107, 2016). "CD34+CD38− cells have been shown to be able to initiate acute myeloid leukemia (AML)." (PMID 28018598, 2016). "This was accomplished by Bonnet and Dick in acute myeloid leukemia (AML) who showed that small subset of leukemic cells (CD34+CD38−) was able to initiate the disease when transplanted into a NOD/SCID mouse (non-obese diabetic/ severe combined immunodeficient mouse)." (PMID 26593898, 2015). "However, CSCs have been being isolated from more and more cancers, since first discovered in the acute myeloid leukemia (AML) by using CD34++/CD38- biomarkers." (PMID 24564919, 2013). "The study of CSCs began in 1994, when it was reported that CD34/CD38 cells were human acute myeloid leukemia (AML) stem cells." (PMID 35571530, 2022). "Leukemic stem cells (LSCs) were first described in acute myeloid leukemia (AML), where it was demonstrated that CD34+CD38− AML include a subpopulation of LSCs with a capacity to differentiate and self-renew." (PMID 31709180, 2019). "Bonnet and Dick (1997) reported that a small subset of leukemic cells (CD34+CD38-) were capable of initiating human acute myeloid leukemia (AML) in a xenograft mouse model, this provided the first experimental evidence for the existence of cancer stem cells." (PMID 28400729, 2017). "The CSCs of acute myeloid leukemia (AML) have a CD34+CD38- cell surface marker resembling that of normal hematopoietic stem cells (HSCs)." (PMID 28038467, 2017). "Bonnet and Dick first isolated CD34+CD38- cells that are capable of initiating human acute myeloid leukemia (AML)." (PMID 29179522, 2017).
acute myeloid leukemia (continued). "Single cell sorting and culture were performed in the various sets of hematopoietic stem cells including CD34+CD38- acute myeloid leukemia (AML) cell population (ASCs) from a total of 60 patients with AML, and 11 healthy controls." (PMID 25881148, 2015). "Furthermore, Anti-CD47 antibody therapy disrupts the signal on CD34+CD38- leukemic stem cells, enhancing macrophage-mediated phagocytosis and achieving durable remissions in preclinical Acute Myeloid Leukemia (AML) models." (PMID 40881675, 2025). "In contrast, while the CD34+CD38−/dim phenotype with aberrant marker expression (e.g., CD45RA, CD123, or CD26) is well-documented in CML and acute myeloid leukemia, a definitive LSC phenotype for lymphoid leukemia remains undefined." (PMID 40076750, 2025). "In acute myeloid leukemia, the frequency of ALDH1+ cells was found to vary from 1 to 16%, and another study found that CD34+CD38− varied by 1000-fold in a cohort of 16 patients." (PMID 41228340, 2025). "Bonnet and Dick were the first to identify a subpopulation of human acute myeloid leukemia (AML) cells, marked by CD34+ CD38, which were able to induce malignancy in transplanted mice." (PMID 39547513, 2024). "CD38 and CD47 are also expressed in other hematologic cancers, such as T-cell acute lymphoblastic leukemia (T-ALL) and acute myeloid leukemia (AML)." (PMID 38983860, 2024). "A clinical study showed that CD56dimCD16− and CD56brightCD16− NK cells represent the predominant NK cell subpopulations in acute myeloid leukemia (AML) and that CD39+/CD38+ cells cluster on CD56brightCD16− NK cells." (PMID 37834375, 2023). "CRISPR/Cas9 genome editing was applied to disrupt CD38 during amplification, showing that CD38 CAR-NK cell fratricide reduced and augmented abilities to target primary acute myeloblastic leukemia (AML) blasts." (PMID 36797756, 2023). "The CSC population has been identified in acute myeloid leukemia (AML) as cells showing CD34 and CD38 expression or co-expression of both markers, CD34/CD38." (PMID 37626893, 2023). "Similarly, transplantation of acute myeloid leukemia (AML) patient-derived CD34+CD38− cells results in the establishment of an AML-like disease including the development of leukemic blasts." (PMID 35990601, 2022). "In hematopoietic malignancies, HCSCs (also known as leukemia stem cells, LSCs) have been identified in acute myeloid leukemia (AML) in the 1990s, with specific markers such as CD34+/CD38−." (PMID 35659296, 2022). "Initially, Dick and colleagues identified the leukemia-initiating cluster of differentiation (CD)-34+ CD38- cells from acute myeloid leukemia (AML) and showed that these cell fractions have differentiation and self-renewal capacities using serial transplantation in immunodeficient mice." (PMID 35155201, 2021). "CSCs were characterized for the first time in acute myeloid leukemia (AML), in which cells with the CD34+/CD38− phenotype exhibited proliferative and self-renewal capacities similar to those of primary stem cells." (PMID 32028565, 2020). "Although CD34+CD38-6, 7, CD133+8 and CD44+CD24-9-11 have been widely used as CSCs markers in human acute myeloid leukemia, brain tumor and breast cancer respectively." (PMID 31892981, 2020). "They separated patient-derived acute myeloid leukemia (AML) cells based on the expression of CD34 and CD38, which are the important markers for detection of immature cells in normal bone marrow." (PMID 35582573, 2019). "In the 1990s, the theory of a hierarchical organization within tumors was introduced in acute myeloid leukemia (AML), identifying leukemia-initiating cells via their expression of a CD34++CD38− phenotype." (PMID 29922594, 2018). "The identification of a small population of cells enriched with a tumor-initiating potential was first reported in Acute Myeloid Leukemia (AML) and it was based on the expression pattern of cell adhesion markers CD34 and CD38." (PMID 27457474, 2016).